CXCR1 (C-X-C motif chemokine receptor 1)
Diseases named in the same sentence as CXCR1 in open-access papers (continued):
Sharing a sentence is not in itself a finding about the gene and the disease.
tumor (continued). "Combined, these data indicate that ASCs are attracted by tumour-secreted CXCL1 synergistically acting through CXCR1 and CXCR2." (PMID 27241286, 2016). "High epithelial CXCL1 and high stromal CXCR1 expression was also observed for all tumours from patients with metastasis who were still alive at the time of array assembly (data not shown)." (PMID 27241286, 2016). "Studies have also shown that CXCL8, CXCR1, and CXCR2 have been associated with tumor progression in melanoma by means of affecting the growth of the tumor cells, angiogenesis, and metastasis." (PMID 27379162, 2016). "CXCL1, CXCL2, and CXCL3 expression was higher and CXCR1 expression was lower in tumor tissues during HCC progression compared with the controls." (PMID 27682863, 2016). "We show that obese patients have increased CXCL1 expression in the prostate epithelium, increased systemic ASC mobilization and increased infiltration of CXCR1-expressing cells in the tumour stroma." (PMID 27241286, 2016). "Analysis of 36 prostate samples in a tissue microarray revealed that CXCR1-bright stroma was present in tumours of three out of three patients who subsequently died from cancer, while it was variable in other cases and absent in normal prostate controls." (PMID 27241286, 2016). "Specifically, the chemokine‐related genes, CXCL1, CXCL2, CXCL3, and IL‐1β, were up‐regulated, while CXCR1 was down‐regulated in tumor tissue during the progression of HCC." (PMID 27682863, 2016). "Collectively, these studies demonstrate that IL-8-driven cancer stemness appears to be a common mechanism that is conserved across multiple tumor types, and, importantly, that this mechanism is amenable to therapeutic intervention via CXCR1/2 inhibition." (PMID 27348007, 2016). "Recruitment to CXCL1-sh-RM1 tumours was also reduced by 2-fold for control ASCs and by 10-fold for CXCR1/CXCR2 knockdown ASCs." (PMID 27241286, 2016). "Confirming αSMA+ stromal cells being largely of ASC origin, in control tumours, the majority of αSMA+ cells were found to also express CXCR1+, while this coincidence of expression was significantly reduced in CXCL1-sh-RM1 tumours." (PMID 27241286, 2016). "The initially secreted chemokines at the tumor site play a key role defining the composition of the tissue stroma and recruiting tumor infiltrating leukocytes bearing specific chemokine receptors (CXCR1, CXCR2, CCR2, CCR4, or CCR5, among others)." (PMID 25688243, 2015). "The available data indicate that IL-8, expressed by tumour cells and induced by chemotherapeutic treatment, is a key regulator of the survival and self-renewal of the population of CXCR1-expressing CSC." (PMID 26517518, 2015). "The PI3K/Akt pathway is one of the principal downstream effectors of IL-8-dependent, CXCR1/2-mediated signaling, leading to tumor progression." (PMID 25871388, 2015). "Activation of the CXCR1/2 signaling by IL-8 leads to activation of NF-κB, forming a positive feedback loop further promotes tumor development." (PMID 25871388, 2015). "We also elucidate the molecular mechanism by which CXCR1/2 antagonism with G31P inhibits downstream signaling during tumor proliferation and metastasis." (PMID 26087179, 2015). "Higher expressions of CXCR1, CXCR2, and CXCR4 with their ligands CXCL5, CXCL8, and CXCL12 appear to be associated with tumor angiogenesis, metastasis, and poor survival in NSCLCs." (PMID 25271023, 2014). "In cervical carcinoma, hypoxia stimulates tumor cells to express high levels of CXCR1/2 and CXCL8 that respond to ligands in the microenvironment by proliferating." (PMID 25110692, 2014). "Interleukin-8 (IL-8) is a CXC-type chemokine that has multiple functions within the tumor microenvironment; promoting cell growth, invasion and metastasis of cancer cells through binding its receptors, CXCR1 and CXCR2 in an autocrine fashion." (PMID 24932473, 2014).
tumor (continued). "The CXCR1 inhibitor repertaxin killed bulk tumor cells by upregulating Fas expression and also prevented IL-8 signaling through CXCR1 to kill the CSCs." (PMID 23986719, 2013). "Since CXCR1 and CXCR2 receptors are expressed on cancer cells, endothelial cells, neutrophils, and tumor-associated macrophages, the synthesis and secretion of CXCL8 from tumor cells affects the tumor microenvironment." (PMID 24224100, 2013). "A collection of in vitro studies have illustrated the anti-tumor potential of CXCR1/2 neutralizing antibodies." (PMID 24276377, 2013). "Pre-clinical studies from numerous groups have demonstrated the ability of CXCR1/2 inhibitors to sensitize multiple tumor models to a plethora of clinically-relevant chemotherapies." (PMID 24276377, 2013). "Our studies appear to represent one of only three pathways identified thus far that strongly suppress tumour initiation activity through mechanisms relevant to BLBCs, with the other two being inhibition of Notch signalling and of the CXCR1 chemokine receptor." (PMID 23606532, 2013). "Of note, their cognate G-protein-coupled receptors (GPCR), CXCR1 and CXCR2, are expressed on endothelial cells, tumor cells, and neutrophils/tumor-associated-macrophages, indicative of pleiotropic activities of IL-8." (PMID 23967403, 2013). "The expression of the CXC (ELR+) family members (CXCL1-3/GROα-γ, CXCL8/IL-8, CXCR1/2) was examined in a series of resected fresh frozen NSCLC tumours." (PMID 21298036, 2011). "Likewise, CXCR1 or CXCR2 expression enabled CAR-T cells to follow tumor-derived IL-8 signals, improving migration and tumor control." (PMID 41596556, 2026). "Furthermore, increased expression of SIGLEC15 was associated with higher levels of PD-1, FOXP3 and, CXCR1, and lower levels of CD69 in tumor tissues." (PMID 41158758, 2026). "Enhancing solid tumor penetration may be achieved either by chemokine receptor engineering (CXCR4, CXCR1) to improve homing, or by altering the tumor microenvironment for improved immune infiltration." (PMID 41487532, 2025). "In addition, G31P-mediated CXCR1/2 inhibition disrupts the pathological feedback loop in the tumor microenvironment, where ELR+ CXC chemokines (CXCL1/8) activate CXCL8, leading to EGFR transactivation and sustained inflammatory signaling." (PMID 41425704, 2025). "Elevated CXCR1 correlated with poorer tumor differentiation and reduced sensitivity to standard chemotherapy regimens (FOLFOX/XELOX), indicating that chemokine pathways may contribute to therapy resistance in this subgroup." (PMID 40943634, 2025). "Compared with untreated controls, tumour-bearing mice treated with navarixin—an orally bioavailable small-molecule antagonist of CXCR1/2—or with thrombospondin-1 (TSP-1), which simultaneously blocks CD47 on tumour cells and CD36 on macrophages, presented significantly reduced tumour volumes." (PMID 41163221, 2025). "Once carcinoma has disseminated throughout the peritoneal cavity, IL-8 binds to CXCR1 on tumor cells triggering the signaling cascade and amplifying aggressive tumor growth, metastasis, and fibrosis, ultimately leading to tumor growth, disease progression, peritoneal spread in PC." (PMID 41002568, 2025). "Moreover, tumor cells induce tumor-associated neutrophils to release neutrophil extracellular traps (NETs) through autocrine signaling via IL-8/CXCL8, CXCR1/CXCR2 agonists, G-CSF, and TGF-β pathways." (PMID 40563367, 2025). "For several solid tumors with high levels of CXCL8, including pancreatic, breast, and ovarian cancer cells, enforced expression of CXCR1 or CXCR2 in A20-28z CAR-T cells showed a higher infiltration proportion in the tumor core, with altered specificity or cytolytic activity." (PMID 40148310, 2025).
tumor (continued). "The IL-8/CXCR1 axis not only supports tumor growth and metastasis but also creates a pro-tumorigenic microenvironment by modulating the behavior of immune cells within the tumor milieu." (PMID 38891100, 2024). "However, the results herein demonstrated that, despite inhibiting tumor growth, CXCR1 was more effective in regulating EMT marker expression than CXCR2." (PMID 39766038, 2024). "Notably, we identified EGFR-related ligand-receptor pairs in CXCR1+ neutrophils and tumor cells, which were further enhanced in resistant samples, potentially contributing to EGFR-TKI resistance through sustained EGFR activation." (PMID 39638994, 2024). "For example, IL-8 produced by immunosuppressive cells like cancer cells, mast cells, macrophages, and neutrophils can promote TCSCs self-renewal, sphere formation, and tumor initiation capacity by attaching to TCSCs cell surface CXCR1 and CXCR2 via autocrine or paracrine pathways." (PMID 39776907, 2024). "We next determine whether the inhibition of tumor growth in CXCR1-expressing cells correlated with a decrease in VEGF expression." (PMID 39766038, 2024). "Furthermore, ligand-receptor pairs related to EGFR between CXCR1+ neutrophils and tumor cells were significantly increased in resistance and communication with Treg cells also increased." (PMID 39638994, 2024). "Interestingly, the overexpression of ITM2A in MDA-PCa-2b cells (MDA-PCa-2b-ITM2A-GFP) inhibited tumor growth similar to that of MDA-PCa-2b-CXCR1." (PMID 39766038, 2024). "However, the overexpression of ITM2A in MDA-PCa-2b cells decreased tumor growth similar to that of MDA-PCa-2b-CXCR1 cells." (PMID 39766038, 2024). "In pre-clinical studies, blocking IL-8 signaling with the CXCR1/2 small-molecule inhibitors SX-682 or reparixin resulted in increased antitumor immunity and significantly slower tumor growth in gastric cancer, pancreatic cancer, squamous cell carcinoma, NSCLC, glioma and hepatocellular carcinoma." (PMID 39123403, 2024). "Therefore, we utilized the syngeneic MOC1 murine model of HPV-negative HNSCC both subcutaneously and orthotopically to elucidate how CXCR1/2 inhibition plus docetaxel reshapes the tumor immune microenvironment." (PMID 39639338, 2024). "Using the NOD scid gamma (NSG) mouse model, we subsequently assessed whether the increased population of intratumor NK cells observed in the MDA-PCa-2b-CXCR1 xenografts was the major contributing factor for the marked inhibition of its tumor growth." (PMID 39766038, 2024). "In the same study, CXCR2+ MPO+ (Myeloperoxidase) cells infiltrated spontaneous intestinal tumors in Apcmin/+ and AhCreER; Apcfl/+; Ptenfl/fl mice and CXCR1/2 blocking pepducin treatment suppressed tumor infiltration of MPO+ cells and adenoma formation concurrently." (PMID 38786066, 2024). "In addition, simultaneous inhibition of CXCR1/2 signaling by SX-682 and inhibition of TGFβ and PD-L1 signaling synergized to reduce mesenchymal tumor features in murine models of breast and lung cancer." (PMID 39123403, 2024). "CXCR1, in association with ligand IL8, controls the leukocyte transmission into tumor cells, modifies tumor immune response, regulates angiogenesis, increases tumor growth and survival, and promotes metastasis." (PMID 38388460, 2024). "Increased CXCR1 expression might be a factor in this inflammatory reaction which in the context of cancer can affect tumour growth, invasion and progression." (PMID 38426619, 2024). "ELR+ CXCLs/CXCR1/2 signaling promotes tumor progression through multiple signaling pathways." (PMID 39769501, 2024). "Additionally, IL-8 levels in MPE fluid versus serum, along with immunohistochemical expression of IL-8/CXCR1 signaling in tumor tissue and cell blocks were analyzed." (PMID 38891100, 2024).
tumor (continued). "Based on the analysis of the percentage of elevated concentrations, we indicated that the combined analysis of CXCL1 and CXCR1 with the classical tumor marker might be more useful in the diagnosis of CRC in comparison to the measurement of a single biomarker." (PMID 37509572, 2023). "In addition, harnessing a monoclonal antibody, Y3041658, for effective antagonization of human CXCR1/2 is also a promising strategy to impair GROα-mediated tumor-promoting effects." (PMID 36624516, 2023). "CXCR1 KD and repertaxin inhibition of tumor growth in vivo is vital." (PMID 36831112, 2023). "The deletion of Cxcr1/2 did not alter the growth rate of ID8 cells but caused the loss of the tumor-promoting effect on cancer cell dissemination and progression in the GROα-enriched TME." (PMID 36624516, 2023). "Similarly, IL-8 can enhance tumor proliferation through the CXCR1/2 receptor on the tumor cell, thus recruiting myeloid-derived suppressor cells (MDSC) and neutrophils to TME, where an immunosuppressive microenvironment is formed." (PMID 38455086, 2023). "CXCR1/2 can recruit neutrophils from the blood vessel into the tumor." (PMID 37540227, 2023). "In addition, CXCR1 and CXCR2 are also expressed in different cells, such as tumor cells, tumor-associated mesenchymal stromal cells (MSCs), and endothelial cells." (PMID 37765018, 2023). "In addition, overexpression of CXCL8 and CXCR1 or CXCR2 led to tumor cell growth and metastasis via activating PI3K/AKT and ERK1/2 MAPK signaling." (PMID 36612163, 2022). "Notably, CXCL8 binds CXCR1/2 in the tumor microenvironment, promoting tumor cell proliferation and growth through autocrine and paracrine mechanisms." (PMID 36072669, 2022). "For instance, IL-8 (CXCL8) promotes tumor angiogenesis by binding to CXCR1 and CXCR2 receptors." (PMID 36246978, 2022). "Indeed, tumor progression was remarkably attenuated by the CXCR1/2 inhibitor Reparixin, whereas inhibition of NF-κB had limited effect given the involvement of multiple signaling pathways." (PMID 35130902, 2022). "Providing further insights on the role of the IL-8/CXCR1/2 axis within the tumor microenvironment, we also assessed that the paracrine actions elicited by the conditioned medium collected from the AGEs-stimulated CAFs are no longer evidently inhibiting this axis." (PMID 35954247, 2022). "However, this blockade of CXCR1/2 also enhances tumor infiltration, activation, and therapeutic efficacy of adoptively transferred murine NK cells, suggesting that cellular therapies can be improved by therapeutic modulation of the tumor environment." (PMID 35937775, 2022). "Notably, PPBP (also known as CXCL7) is a critical chemokine ligand that plays a critical role in promoting tumor proliferation through the CXCL7/CXCR1/2 signaling pathway." (PMID 35711675, 2022). "Previous research found that the tumor-associated MSCs produced chemokines Gro-α/CXCL1, Gro-β/CXCL2, and IL8, which bound to the CXCR1/2 receptor on the surface of tumor cells and led to the formation of chemoresistance and induced the polarization of macrophages." (PMID 36354566, 2022). "Furthermore, various neutrophil-attracting chemokines (CXCL1, CXCL2, CXCL5, CXCL6, and CXCL8) promote the migration of neutrophils to the tumor site through CXCR1 and CXCR2 receptors." (PMID 36091114, 2022). "Moreover, chemokines produced by tumor cells, such as the CXCL1,2,5,8/CXCR1/2 signaling axis, can promote neutrophil recruitment, forming positive feedback with the tumor-promoting effect of TANs." (PMID 36230676, 2022). "Defective expression of chemokine receptors CXCR1 and CXCR2 on the surface of LDNs was linked to a reduced in vitro migratory potential toward tumor-conditioned media in migration assays with LDNs from cancer patients and tumor-bearing mice." (PMID 35328639, 2022).
tumor (continued). "With the aim to overcome the deleterious effects of neutrophils in cancer, the IL-8 and CXCR1/CXCR2 inhibition could reduce neutrophils migration to the tumor, thus avoiding NETs formation and eventually preventing drug resistance." (PMID 36591453, 2022). "Inhibition of CXCR1 decreased neutrophil attraction, proliferation, and formation of a tumor mass." (PMID 34503058, 2021). "CXCR1 and CXCR2 are receptors for IL-8 (CXCL8), an inhibitory chemokine involved in recruitment of tumor-associated neutrophils or myeloid derived suppressor cells (MDSCs), tumor proliferation and angiogenesis." (PMID 33746981, 2021). "Therefore, co-localization of T cells and tumor cells were able to be detected by living imaging, and effects of CXCR-1 and CXCR-2 on T cell trafficking were observed directly." (PMID 33777013, 2021). "Also, T cells engineered to express CXCR2 or CXCR1 have greater capacity for homing and infiltration of tumor in murine models." (PMID 34454518, 2021). "CXCR1/2 inhibitors (SX-682) significantly abrogated MDSCs trafficking within a tumor and improved tumor infiltration, activation, and therapeutic efficacy of adoptively transferred murine NK cells in the HNSCC preclinical model, and in combination with anti-PD-1, they improved ICI therapy." (PMID 34025641, 2021). "However, we assume that the CXCR1 expression in vivo is generally increased, and therefore, appears to be expressed at the same density as seen in primary tumor cells." (PMID 34070094, 2021). "Our observations that CXCL1 and IL-8 are enhanced by the inclusion of stromal cells in 3D cultures of CRC cells and macrophages indicate that targeting the CXCR1/2 signalling axis may represent a therapeutic target in stromal-dense CRC tumours." (PMID 34885111, 2021). "Waugh and Wilson reported IL-8 secreted by tumor cells plays an important role in the tumor microenvironment and observed that the expressions of the IL-8 receptors, CXCR1 and CXCR2, were elevated in cancer cells, endothelial cells, and tumor-infiltrating neutrophils and macrophages." (PMID 34267603, 2021). "CXCR1 has been shown to contribute to angiogenesis and tumor progression." (PMID 33936029, 2021). "Moreover, OS of tumor-bearing mice was significantly improved under therapy with CAR T CXCR1 and CXCR2." (PMID 34203660, 2021). "We speculate that CXCR1/2 may achieve an anti-tumor effect by increasing immune cell infiltration into the sites of tumor cells." (PMID 33324682, 2020). "CXCR1 or CXCR2 modified CAR T cells were capable of tumor regression in the GBM preclinical model." (PMID 33224149, 2020). "It has been reported that CXCR1/2 are the receptors for IL-8 on tumor cells." (PMID 32471980, 2020). "Indeed, in gastric cancer tissue samples obtained following treatment by the CXCR1/2 inhibitor reparixin, reduced levels of proliferating tumor cells were noted, alongside with reduced presence of PD-L1+ macrophages and increased fraction of CD8+ T cells." (PMID 32582148, 2020). "Our results showed that increased levels of CXCR1/2 ligands may be predictive markers of a tumor’s response to chemotherapy." (PMID 31504643, 2020). "In parallel, inhibition of CXCL8 or of CXCR1/2 has increased the sensitivity of breast tumor cells to chemotherapeutic drugs, accompanied by reduced proportion of CSCs, angiogenesis, tumor growth and/or metastasis, with roles attributed to cyclooxygenase 2 (COX-2) in this process." (PMID 33585241, 2020). "Furthermore, IHC performed on tumour sections confirmed that IR exposure increased Bcl-2 in these PTEN-null tumours, which was again reversed by x1/2pal-i3-mediated inhibition of CXCR1/2 signalling." (PMID 32743555, 2020). "This process is mediated by CXCR1/2, the receptors of IL-8 on tumor cells." (PMID 32471980, 2020). "TANs are recruited in the tumor environment mainly via the chemokine (CK) receptors CXCR1 and CXCR2, although many other CKs and coupled receptors could be involved." (PMID 31991796, 2020).